PPP2R3B (protein phosphatase 2 regulatory subunit B''beta)
Description:
The B regulatory subunit might modulate substrate selectivity and catalytic activity, and might also direct the localization of the catalytic enzyme to a particular subcellular compartment.
Synonyms: PPP2R3L; PPP2R3LY; PR48; PR70; NYREN8
Tractability: PROTAC: ubiquitination databases record sites on it.
Gene: Protein-coding gene on chromosome X (333,933 to 386,955, reverse strand). Ensembl gene ENSG00000167393.
Subcellular location: Nucleus
Subcellular location (Human Protein Atlas): Nucleoplasm; Cytosol; Primary cilium; Primary cilium tip
Pathways (Reactome):
Cell Cycle: Cyclin A/B1/B2 associated events during G2/M transition; Cyclin D associated events in G1; Inhibition of replication initiation of damaged DNA by RB1/E2F1
Gene Ontology:
Molecular function: protein binding; protein phosphatase regulator activity; calcium ion binding
Biological process: protein dephosphorylation; regulation of cell cycle
Cellular component: nucleoplasm; nucleus; protein phosphatase type 2A complex
Homologues: Orthologues: dog PPP2R3B (78% identical), pig PPP2R3B (75% identical), tropical clawed frog ppp2r3b (65% identical). Paralogues in human: PPP2R3A (51% identical).
Diseases named in the same sentence as PPP2R3B in open-access papers:
PPP2R3B is named in the same sentence as 15 diseases in open-access papers, as found by Europe PMC text mining. Sharing a sentence is not in itself a finding about the gene and the disease. The quoted sentences say what the papers report.
pancreatic cancer (2 papers, 2021 to 2023). "GNB3, PPP2R3B and TSC1 were highly expressed in the LRS group, suggesting that these genes may be tumor suppressors of pancreatic cancer." (PMID 37124502, 2023).
chronic tic disorder (1 paper, 2018). A neurological disorder presenting in childhood that is characterized by either motor or phonic tics, but not both, that occur daily or nearly daily for at least a year and are not attributed to an identifiable cause. "Both ZBED1 and PPP2R3B may have a role in the regulation of cell growth and division, and AKAP17A has been associated with chronic tic disorder." (PMID 30213969, 2018).
Kyphoscoliosis (1 paper, 2023). An abnormal curvature of the spine in both a coronal (lateral) and sagittal (back-to-front) plane. "Therefore, ppp2r3b−/− mutant zebrafish exhibit adolescent onset and progressive kyphoscoliosis, which is fully penetrant and reminiscent of human IS." (PMID 37100808, 2023).
melanocytic nevus (1 paper, 2021). A neoplasm composed of melanocytes that usually appears as a dark spot on the skin. "Our data demonstrate that PPP2R3B overexpression promotes proliferation of NRAS-mutant melanoma cell lines, which could explain the predisposition to the development of a clinically apparent melanocytic nevus or melanoma in the context of a somatic pathogenic variant in a melanocyte." (PMID 34145395, 2021).
melanoma (1 paper, 2021). A malignant, usually aggressive tumor composed of atypical, neoplastic melanocytes. "Using published data of whole-genome transcriptomic profiling of 703 melanomas, increased tissue expression of PPP2R3B was significantly associated with prolonged MSS." (PMID 34145395, 2021). "We identify here germline duplications in the gene PPP2R3B predisposing to nevogenesis and melanoma in an important proportion of cases." (PMID 34145395, 2021). "The effects and mechanisms of PPP2R3B overexpression were modeled in detail by creation of a stable inducible overexpression system in two NRAS-mutant melanoma cell lines SKMEL2 and SKMEL30." (PMID 34145395, 2021). "Extensive modeling of the biology of PPP2R3B overexpression demonstrated promotion of proliferation and reduction of migration in melanoma cells." (PMID 34145395, 2021). "Unlike many known expression-survival associations in melanoma, transcriptomic pathway analysis did not support an immune pathway-mediated effect, leading us to look for an alternative mechanism of action of PPP2R3B overexpression on melanocytic proliferation." (PMID 34145395, 2021). "As our patients with duplications were however of both sexes, and the correlation between PPP2R3B expression and survival in the melanoma trancriptomic data was independent of sex, we do not currently have any evidence for such an effect." (PMID 34145395, 2021).
scoliosis (1 paper, 2023). A congenital or acquired spinal deformity characterized by lateral curvature of the spine. "Using in situ hybridisation, we noted some locations of PPP2R3B expression that are potentially relevant to scoliosis." (PMID 37100808, 2023).
tumor (3 papers, 2016 to 2023). "Being that several PAR genes are implicated to function as tumor suppressors, such as PPP2R3B, SHOX, SLC25A6, ASMT, and DHRSX, they serve as prime candidates for further investigation and may hold the greatest therapeutic promise." (PMID 27655702, 2016).
cancer (2 papers, 2021 to 2022). A tumor composed of atypical neoplastic, often pleomorphic cells that invade other tissues. "Mutations in PPP2R3B in human cancer are rare; however, it has been documented that loss of the inactive X chromosome is high in females with breast, ovarian, and melanoma tumors." (PMID 36328247, 2022). "Analysis of the TCGA database demonstrates that copy-number variants including PPP2R3B are more common across cancers in general than single-nucleotide variants, suggesting that dosage of PPP2R3B is relevant in cancer development." (PMID 34145395, 2021).
hematological malignancies (1 paper, 2016). "For example, if haploinsufficiency of PPP2R3B, a subunit of PP2A, aids in the development of hematological malignancies, this could expand the applications for pharmacological activators of PP2A, which are being explored in preclinical AML models." (PMID 27655702, 2016).
PPP2R3B also shares sentences with these, for which no sentence is quoted: congenital melanocytic nevi (1 paper); dyschondrosteosis (1); idiopathic scoliosis (1); muscular dystrophy (1); ovarian carcinoma (1); spinocerebellar ataxia (1).